MIR517A (microRNA 517a)
Synonyms: hsa-mir-517a; MIRN517A; mir-517a
Gene: MicroRNA gene on chromosome 19 (53,712,268 to 53,712,354, forward strand). Ensembl gene ENSG00000207734.
Gene Ontology:
Biological process: miRNA-mediated post-transcriptional gene silencing
Homologues: Orthologues: chimpanzee ptr-mir-517a (100% identical), macaque mml-mir-517a (93% identical). Paralogues in human: MIR519A2 (86% identical), MIR518E (85% identical), MIR521-1 (85% identical), MIR516A1 (84% identical), MIR518F (84% identical), MIR519C (84% identical), MIR520C (84% identical), MIR522 (84% identical), MIR523 (84% identical), MIR516A2 (83% identical), MIR516B1 (83% identical), MIR518C (83% identical), and 12 more.